HSPA8 (heat shock protein family A (Hsp70) member 8)
Diseases named in the same sentence as HSPA8 in open-access papers (continued):
Sharing a sentence is not in itself a finding about the gene and the disease.
Stroke (8 papers, 2015 to 2025). Sudden impairment of blood flow to a part of the brain due to occlusion or rupture of an artery to the brain. "HSPA8 is involved in many stroke-associated cellular processes, playing a pivotal role in the protein quality control system." (PMID 37372351, 2023). "A genome-wide association study reported that HSPA8 is associated with the new onset of atrial fibrillation, MI, acute kidney injury, and stroke after cardiac surgery, thereby indicating its potential role in cardiac protection." (PMID 34178482, 2021). "We identified several potential loci, in particular PHLPP2, BBS9, RyR2, DUSP4 and HSPA8, associated with new-onset of atrial fibrillation, delirium, myocardial infarction, acute kidney injury and stroke after cardiac surgery." (PMID 30678657, 2019). "It has been shown that the expression of the HSPA8-ps1 gene is increased in the cerebral cortex affected by a stroke." (PMID 35054033, 2022).
depression (7 papers, 2012 to 2025). "The findings revealed that, even after factoring in depression, the previously established associations for HSPA8 and SKP1 remained statistically significant." (PMID 38115821, 2023). "In addition, a reduced level of Uqcrb in both the depression-susceptible and anxiety-susceptible groups, and elevated levels of Echs1 and Hspa8 in both the anxiety-susceptible and insusceptible groups were found as compared to the control group." (PMID 33737865, 2021). "Although a role for these particular heat-shock proteins in human depression has yet to be identified, preclinical models have identified HSPA8 and HSPD1 as proteins regulated subsequent to chronic stress." (PMID 24040027, 2013). "Furthermore, genes (TNRC6B, HSPA8), and pathways (FoxO- and Hippo signaling pathway) were predicted to be relevant in the pathway regarding the influence of depression on bone metabolism." (PMID 39869252, 2025). "ACTB, CKB, NEFL, INA and GFAP had link to both schizophrenia and depression, while CTSD, HSPA8, NEFM and TUBA1A had link to schizophrenia." (PMID 23272063, 2012). "Studies in patients of HCC with moderate/severe or mild/no depression have found that the high expression of HSPA8 is related to the activation of VEGF/VEGFR2–PI3K–AKT pathway." (PMID 36452344, 2022).
pancreatic cancer (7 papers, 2013 to 2025). "HSPA8 overexpression promotes cell viability and autophagy in pancreatic cancer cells." (PMID 38419499, 2024).
lung carcinoma (6 papers, 2016 to 2025). "We identified several CRC-associated proteins, e.g., FN1, HSPA8, and TLN1, in the blood plasma obtained from patients with lung cancer." (PMID 37241967, 2023). "Intriguingly, it was shown that the levels of HSPA8 (HSC70) in the plasma measured by ELISA were dramatically decreased in lung cancer patients compared to healthy controls." (PMID 34684727, 2021). "The content of HSPA8 was approximately the same for the two histological lung cancer subtypes (39.1 ± 16.8 nM in LAC samples (N = 15) vs. 34.6 ± 15.2 nM in SqC samples (N = 11))." (PMID 34684727, 2021). "We designed rescue experiments to explore whether circRREB1 regulates PINK1 protein expression through HSPA8, which in turn regulates mitophagy to promote lung cancer development." (PMID 40653497, 2025). "By querying TCGA database, we found that HSPA8 expression is increased in lung cancer patients and that the group with high expression of HSPA8 has a poorer survival rate than the group with low expression, which is consistent with the role of circRREB1 as an oncogenic factor." (PMID 40653497, 2025). "In summary, circRREB1 may increase the expression level of PINK1 by targeting HSPA8, thereby inducing mitophagy and ultimately promoting the development of lung cancer." (PMID 40653497, 2025). "By applying targeted mass spectrometry with stable isotope-labeled peptide standards, we assessed the levels of 28 EV-associated proteins, including the conventional exosome markers CD9, CD63, CD81, CD82, and HSPA8, in vesicles derived from the lung cancer cell lines NCI-H23 and A549." (PMID 34684727, 2021). "Mechanistically, circRREB1 binds to HSPA8, which in turn increases the expression of PINK1, promotes mitophagy and ultimately promotes the development of lung cancer." (PMID 40653497, 2025). "The abundance of TLN1, TUBA4A, HSPA8, ITGB3, TSG101, and PACSIN2 in the plasma of lung cancer patients was measured using targeted mass spectrometry and compared to that in plasma from healthy volunteers." (PMID 34684727, 2021). "For instance, we identified three heat shock protein (HSP) genes, HSP 90 alpha family class B member 1 (HSP90AB1), HSP family A member 8 (HSPA8), and HSP family A member 5 (HSPA5), as novel biomarkers in lung cancer and GBM." (PMID 33277589, 2020). "Mechanistically, m5C-modified circRREB1 stabilizes the HSPA8 protein by inhibiting its ubiquitination, thereby increasing the expression of PINK1, initiating mitophagy, and ultimately promoting the progression of lung cancer." (PMID 40653497, 2025). "Mechanistically, circRREB1 directly binds to HSPA8 and stabilizes it by inhibiting ubiquitin-dependent degradation, thereby inducing mitophagy through the HSPA8/PINK1/Parkin signalling axis and ultimately promoting the development of lung cancer." (PMID 40653497, 2025). "Together, these observations suggest that FN1, TLN1, ITGB3, HSPA8, and TUBA4A detection in the blood using SRM/SIS may serve as an indicator of tumors, and elevations in their concentrations coupled with PACSIN2 detection discriminate lung cancer from other malignancies." (PMID 34684727, 2021).
schizophrenia (6 papers, 2012 to 2025). A major psychotic disorder characterized by abnormalities in the perception or expression of reality. "Furthermore, studies that explore the functional contribution of the HSPA8 variants to schizophrenia pathogenesis are also needed." (PMID 34932194, 2022). "The present study attempted to determine whether HSPA8 polymorphisms are associated with a susceptibility to schizophrenia or whether they have an impact on the clinical parameters of the disease in a Polish population." (PMID 34932194, 2022). "This implies that the genetic variants of HSPA8 might contribute to schizophrenia pathogenesis." (PMID 34932194, 2022). "We transformed these proteins to their encoding gene IDs and identified the top 20 genes as the most probable schizophrenia-risk genes, including the EYA3, CNTN4, HSPA8, LRRK2, and AFP genes." (PMID 37966892, 2023). "Several studies have also found that the popular antipsychotic drugs (haloperidol, clozapine, olanzapine, risperidone) affect the expression of the HSPA8 gene/protein, which indicates that HSPA8 may potentially be involved in the treatment of schizophrenia." (PMID 34932194, 2022). "Another study also revealed downregulation of HSPA8 and NPM1 within layer 2 of the insular cortex, which is closely related to auditory hallucinations and language, in patients with schizophrenia." (PMID 29514709, 2018).
COVID-19 (5 papers, 2022 to 2025). A disease caused by infection with severe acute respiratory syndrome coronavirus 2. "Second, rs1136141 HSPA8 is associated with increased risk of severe COVID-19 in patients under 68 years of age as well as in patients with inadequate intake of fresh fruit and vegetables." (PMID 41009536, 2025). "First, rs1461496 HSPA8 is linked to an increased risk of severe COVID-19 in patients aged 68 and over, while it is also associated with reduced time to the start of clot growth in the entire group (Tlag, minutes)." (PMID 41009536, 2025). "Next, we established associations of HSPA8 SNPs with severe COVID-19, as well as with clinical manifestations." (PMID 41009536, 2025). "Moreover, the protective allele G rs1461496 HSPA8 creates DNA-binding sites for TFs involved in biological processes that may have a positive impact on COVID-19." (PMID 41009536, 2025). "Specifically, the polymorphic variants rs1136141 and rs1461496 HSPA8, rs1042665 HSPA9, rs7189628 DNAJA2, rs910652 HSPA12B, rs6457452 HSPA1B and rs1043618 HSPA1A are associated with alerted risk of severe COVID-19." (PMID 41009536, 2025). "In developing a potent COVID-19 prophylactic, targeting the viral spike protein that binds HSPA8 during the virus’s lifecycle is preferable." (PMID 39599841, 2024). "The HSPA8 protein involved in antigen processing and presentation was changed in six COVID-19 individuals." (PMID 37521843, 2022). "Notably, two SNPs rs1136141 HSPA8 and rs7189628 DNAJA2 are associated with severe COVID-19 in patients under 68 years of age, whereas in older patients, SNPs rs1461496 HSPA8, rs910652 HSPA12B, rs1043618 HSPA1A and rs6457452 HSPA1B are significantly associated with severe disease." (PMID 41009536, 2025). "Conversely, in patients under 68 years old, SNPs rs1136141 HSPA8 (risk allele A, OR = 1.55, 95% CI 1.06–2.28, p = 0.02, pperm = 0.02) and rs7189628 DNAJA2 (risk allele T, OR = 2.02, 95% CI 1.08–3.75, p = 0.03, pperm = 0.02) increased the risk of severe COVID-19." (PMID 41009536, 2025).
gastric cancer (5 papers, 2019 to 2026). A primary or metastatic malignant neoplasm involving the stomach. "These four proteins, including DLL3, IL-33, LG3BP, and HSPA8, could be a new insight into and promising diagnostic or therapeutic targets of stomach cancer." (PMID 35382168, 2022). "In gastric cancer, HSPA8 interacts with GKN2 to promote oxidative stress-induced apoptosis, inhibit the NF-κB signaling pathway, and activate the JNK signaling pathway." (PMID 34168974, 2021). "Moreover, gene expressions of DLL3, IL-33, LG3BP (also LGASLS3BP), and HSPA8 were analysed in UCSC Xena Functional Genomics Explorer based on the TCGA data set from 415 primary tumor samples of stomach cancer and 35 normal tissues." (PMID 35382168, 2022).
glioblastoma (5 papers, 2017 to 2021). The most malignant astrocytic tumor (WHO grade IV). "In a previous study, HSPA8 was found to be important for glioblastoma, and knockdown of HSPA8 interferes with the tumorigenic properties of glioblastoma cells ectopically overexpressing nesting proteins." (PMID 34168974, 2021). "The regulating mechanisms HSPA8 were reported in malignancies like glioblastoma and myeloid leukaemia." (PMID 30027097, 2018). "In glioblastoma cells, Nestin regulates growth, stemness, and invasion through the alteration of HSC71 (gene HSPA8)." (PMID 32429463, 2020).
Huntington disease (5 papers, 2015 to 2025). Huntington disease (HD) is a rare neurodegenerative disorder of the central nervous system characterized by unwanted choreatic movements, behavioral and psychiatric disturbances and dementia. "Additionally, the decreased ACBD5 expression level was associated with Huntington’s disease, while high GABARAPL1 and HSPA8 expression levels were concentrated in ECM receptor interaction." (PMID 40002775, 2025).
ischemia (5 papers, 2013 to 2023). A hypoperfusion of the BLOOD through an organ or tissue caused by a PATHOLOGIC CONSTRICTION or obstruction of its BLOOD VESSELS, or an absence of BLOOD CIRCULATION. "Altogether, these data indicate that HSPA8 may take an important place during the cellular response to ischemia, and future research should address its role in the course of IS." (PMID 37372351, 2023). "Upregulated HSPA2 exerted a neuroprotective effect through its regulation of endocytosis in a rat middle cerebral artery occlusion model, and inhibition of HSPA8 would protect against spinal ischemia–reperfusion injury via astrocyte NF-κB/NLRP3 inflammasome pathway." (PMID 36120453, 2022). "Thus, HSPA8 plays a critical role in regulating the myocardial innate immune system and cardiac function after ischemia/ reperfusion." (PMID 30678657, 2019). "Given that the association between HSPA8 and Iba-1 was weaker than that of HSPA8 and GFAP immunoreactivity cells, especially after 12 h of reperfusion, we emphasize that HSPA8 of the spinal astrocyte might play an essential role in the pathogenesis of ischemia and reperfusion injury." (PMID 34362408, 2021).
legionellosis (5 papers, 2016 to 2023). Any disease caused by Legionella bacteria. "Our major finding pathways- based network analysis between the patients and a normal one, include antigen processing and presentation (HSPA5, HSPA8), protein processing in the endoplasmic reticulum (HSP90B1, HSPA5, HSPA8) and legionellosis (HSPA8)." (PMID 27895852, 2016). "In addition, HSPA8 and SAR1A connected the protection processing in endoplasmic reticulum with legionellosis pathway." (PMID 32632500, 2020).
neuroblastoma (5 papers, 2007 to 2023). Neuroblastoma (NB) is the most common solid, extracranial childhood tumor. "Using affinity chromatography and mass spectrometry-based protein identification, we have identified cell surface-associated HSPA8 as a binding partner of the human VGF-derived peptide TLQP-21 in SH-SY5Y neuroblastoma cells." (PMID 28934328, 2017). "Since we found that DNAJB6 can decrease tau aggregation in human neuroblastoma cells, we would like to know whether tau, the client, is associated with HSPA8-DNAJB6, the chaperone–cochaperone complex." (PMID 38110916, 2023). "In Cluster 1, transcripts are over-expressed in the mouse neuroblastoma cell lines in a tumor-restricted manner: Chgb, Dus31, 2310042G06Rik, Psma6 (proteasome subunit), Csnk2a1 (casein kinase), Mtrr (metabolic activation), and Hspa8 (heat shock protein)." (PMID 17397536, 2007).
Sepsis (5 papers, 2013 to 2025). Sepsis is defined as life-threatening organ dysfunction caused by a dysregulated host response to infection. "In conclusion, VDAC1, HSPA8, SOD1, HSPA9, TXN, and SNCA have been identified as oxidative stress-related genes associated with sepsis-induced ALI." (PMID 40694561, 2025). "In sepsis, down-regulation of HSPA8 mediates the occurrence of AECs pyroptosis by activating the NLRP3 inflammasome." (PMID 38698431, 2024). "Meanwhile, overexpression of HSPA8 can significantly inhibit the pyroptosis of AECs stimulated by LPS + ATP, thereby alleviating lung injury during sepsis." (PMID 38698431, 2024). "In present study, we showed that when HSPA8 protein levels in sepsis were knockdown by siRNA or inhibited by VER155008, SKP2 protein levels were subsequently reduced." (PMID 38698431, 2024). "We verified that HSPA8 inhibited sepsis-induced lung injury by promoting NLRP3 ubiquitination by constructing pcDNA3.1-HSPA8 and adeno-associated virus AAV9-HSPA8." (PMID 38698431, 2024). "The inhibition of HSPA8 was involved in sepsis induced acute lung injury by promoting pyroptosis of AECs." (PMID 38698431, 2024). "Meanwhile, to detect the protein level of HSPA8 in alveolar epithelial cells during sepsis, lung tissues from Sham and CLP mice were obtained for immunofluorescence." (PMID 38698431, 2024). "This study is the first to focus on the role of HSPA8 in regulating NLRP3 inflammasome activation in AECs in the development of sepsis-induced lung injury." (PMID 38698431, 2024). "This suggests that HSPA8 downregulation plays a role by promoting the degradation of SKP2 in sepsis." (PMID 38698431, 2024). "In sepsis, the suppression of HSPA8 mediates the activation of NLRP3 inflammasome by attenuating ubiquitination modification level of NLRP3." (PMID 38698431, 2024). "This study emphasized the importance of using HSPA8 inhibitors with caution in the context of cytokine storms, which can occur following systemic infections like sepsis and immunotherapies." (PMID 37580406, 2023). "This study aims at investigating the effect of HSPA8 signal activation in AECs on sepsis-induced lung injury, as well as exploring whether HSPA8 is involved in the regulation of E3 ubiquitin ligase SKP2 and NLRP3 inflammasome." (PMID 38698431, 2024). "The data indicates that HSPA8 may mediate the occurrence of sepsis by damaging alveolar epithelial cells." (PMID 38698431, 2024). "The results showe that HSPA8 protein levels are down-regulated in sepsis." (PMID 38698431, 2024). "Thus, we further confirmed that downregulation of HSPA8 in sepsis activated the NLRP3 inflammasome by reducing the ubiquitination level of NLRP3." (PMID 38698431, 2024). "Our findings revealed that both the mRNA expression levels and protein concentrations of HSPA8 and HSPA9 were significantly reduced in the blood samples of patients suffering from sepsis-induced ALI." (PMID 40694561, 2025). "In the present study, we found that the expression of HSPA8 and HSPA9 was significantly reduced in the serum of patients with sepsis-induced ALI compared to healthy individuals." (PMID 40694561, 2025). "The logistic regression algorithm identified 8 genes (VDAC1, HSPA8, SOD1, HSPA9, TXN, NDUFS3, HSP90AB1, SNCA), among which 6 genes were closely correlated with the onset of sepsis-induced ALI (p < 0.05)." (PMID 40694561, 2025). "The expression levels of VDAC1, HSPA8, SOD1, and HSPA9 were significantly decreased in the sepsis-induced ALI group compared to the control group (p < 0.0.5)." (PMID 40694561, 2025). "However, the regulatory mechanism of HSPA8 on SKP2 in sepsis-induced lung injury remains unclear." (PMID 38698431, 2024). "HSPA8 agonist GGA and inhibitor VER155008 were used to investigate the role of HSPA8 in sepsis-induced lung injury." (PMID 38698431, 2024). "In sepsis, HSPA8 interacts with the E3 ubiquitin ligase SKP2, and the down-regulation of HSPA8 promotes the degradation of SKP2." (PMID 38698431, 2024).
Sepsis (continued). "Therefore, we next analyzed the expression of VDAC1, HSPA8 and HSPA9 in the blood samples of patients with sepsis-induced ALI at the clinical level." (PMID 40694561, 2025). "Finally, we analyzed the expression of VDAC1, HSPA8, SOD1, HSPA9, TXN, and SNCA in sepsis-induced ALI in the meta-GEO cohort." (PMID 40694561, 2025). "Co-IP assay showed that there was a significant interaction between HSPA8 and SKP2 in sepsis." (PMID 38698431, 2024). "Therefore, we wondered whether HSPA8, as a major molecule in ubiquitin-protein degradation, has a regulatory role in NLRP3 ubiquitination modification during sepsis." (PMID 38698431, 2024). "In conclusion, the present study demonstrates that the suppression of HSPA8 promotes the degradation of SKP2, which in turn attenuates the ubiquitination and degradation of NLRP3 protein, leading to the activation of NLRP3 inflammasome and subsequent AECs pyroptosis in during sepsis." (PMID 38698431, 2024). "It is not clear whether HSPA8 mediates lung injury by regulating NLRP3 inflammasome in sepsis." (PMID 38698431, 2024). "The proportion of neutrophils exhibited a significant negative correlation with the expression of VDAC1, HSPA8, SOD1, HSPA9 and TXN, and a significant positive correlation with SNCA expression in sepsis-induced ALI." (PMID 40694561, 2025).